SHANK3 (SH3 and multiple ankyrin repeat domains 3)
Diseases named in the same sentence as SHANK3 in open-access papers (continued):
Sharing a sentence is not in itself a finding about the gene and the disease.
autism spectrum disorder (139 papers, 2009 to 2026). A spectrum of developmental disorders that includes autism, and Asperger syndrome. "SHANK3, a synaptic scaffolding protein critical for synapse structure and function, is implicated in autism spectrum disorder (ASD) and Phelan-McDermid Syndrome (PMS)." (PMID 41723111, 2026). "Downregulated DEGs linked to reduced hypersensitivity included Shank3, linked to autism spectrum disorder and pain signaling (Fig. 6J1)." (PMID 41166420, 2025). "White matter abnormalities are consistently observed in Shank3-related autism spectrum disorders (ASD), yet the mechanisms underlying oligodendrocyte dysfunction and myelination deficits remain poorly characterized." (PMID 41203933, 2025). "The resulting deficiency of the postsynaptic density scaffolding protein SHANK3 is associated with autism spectrum disorder (ASD)." (PMID 38858349, 2024). "Shank3, a gene encoding a synaptic scaffolding protein, is implicated in autism spectrum disorder (ASD) and is disrupted in Phelan-McDermid syndrome (PMS)." (PMID 39281868, 2024). "SHANK3 mutations are associated with autism spectrum disorder, and SHANK3 S782A mutation increases SHANK3 enrichment at excitatory synapses in hippocampal neurons." (PMID 39354505, 2024). "SHANK3 gene is a highly replicated causative gene for autism spectrum disorder and has been well characterized in multiple Shank3 mutant rodent models." (PMID 38297387, 2024). "SHANK3 deficiency has been linked to several psychiatric conditions, including autism spectrum disorder (ASD), bipolar disorder, and schizophrenia." (PMID 39363263, 2024). "Phelan-McDermid syndrome (PMS) is caused by monoallelic loss or inactivation at the SHANK3 gene, located in human chr 22q13.33, and is often associated with Autism Spectrum Disorder (ASD)." (PMID 39363263, 2024). "Together, the combined clinical and basic science investigations into SHANK3-associated autism spectrum disorders reveal alterations in cerebro-cerebellar network function, with underlying disruption on the level of synapse structure and function." (PMID 38352654, 2024). "Mutation or deletion of the SHANK3 gene, which encodes a synaptic scaffolding protein, is linked to autism spectrum disorder and Phelan-McDermid syndrome, conditions associated with social memory impairments." (PMID 36991001, 2023). "Clinically, various mutations of the SHANK3 gene are causally associated with brain disorders such as autism spectrum disorders and schizophrenia." (PMID 37187620, 2023). "SHANK3 is an important excitatory postsynaptic scaffold protein, and its mutations lead to genetic cause of neurodevelopmental diseases including autism spectrum disorders (ASD), Philan McDermid syndrome (PMS), and intellectual disability (ID)." (PMID 36221783, 2023). "The SHANK3 gene is linked to autism spectrum disorder and Phelan McDermid syndrome, which have been associated with social memory deficits." (PMID 36991001, 2023). "This stage involves heightened cortical plasticity including homeostatic synaptic scaling, which requires Shank3, a glutamatergic synaptic protein that, when mutated, produces Phelan-McDermid syndrome and is often comorbid with autism spectrum disorder (ASD)." (PMID 36446569, 2022). "Monogenic mutations in SHANK3 gene are among the leading genetic causes of Autism Spectrum Disorders (ASD)." (PMID 36570823, 2022). "Mutations in the SHANK3 gene have been recognized as a genetic risk factor for Autism Spectrum Disorder (ASD), a neurodevelopmental disease characterized by social deficits and repetitive behaviors." (PMID 35022531, 2022). "We observed 424 bidirectionally modulated phosphosites that were strongly enriched for synapse-associated proteins, including S1539 in the autism spectrum disorder-associated synaptic scaffold protein Shank3." (PMID 35471151, 2022). "Those cases with major deletions or truncated nonsense mutations in SHANK3 have been associated with autism spectrum disorders and intellectual disability." (PMID 35328058, 2022).
autism spectrum disorder (continued). "Loss of function of human Shank3 is associated with autism spectrum disorders (ASDs), Phelan–McDermid syndrome, and intellectual disability, indicating that Shank3 plays essential roles within the central nervous system." (PMID 35471151, 2022). "Shank3 is an abundant excitatory postsynaptic scaffolding protein implicated in various neurodevelopmental disorders, including autism spectrum disorder (ASD), Phelan-McDermid syndrome, intellectual disability, and schizophrenia." (PMID 36311023, 2022). "Shank3 is a synaptic protein that is mutated in Phelan-McDermid syndrome and is usually comorbid with autism spectrum disorder (ASD)." (PMID 36446569, 2022). "Phelan-McDermid Syndrome (PMS) is a rare genetic disorder caused by deletion or sequence variation in the SHANK3 gene at terminal chromosome 22 that confers high likelihood of comorbid autism spectrum disorder (ASD)." (PMID 35592263, 2022). "Among the three known Shank family proteins, Shank2 and Shank3 have been associated with various brain disorders, including autism spectrum disorder (ASD), Phelan-McDermid syndrome, intellectual disability, and schizophrenia." (PMID 36311023, 2022). "The SH3 and multiple ankyrin repeat domains 3 (Shank3) protein is a core organizer of the macromolecular complex in excitatory postsynapses, and its defects cause numerous synaptopathies, including autism spectrum disorders." (PMID 33622379, 2021). "Molecular defects of SHANK3 are a well-known cause of several neurodevelopmental entities, in particular autism spectrum disorders and epilepsy, whereas relatively little is known about disease associations of SHANK1." (PMID 34912368, 2021). "Several missense mutations within the canonical SHANK3 isoform have been proposed as causative for the development of autism spectrum disorders (ASDs)." (PMID 33945465, 2021). "Contrasting findings were reported in several animal models with a Shank3 mutation used to induce various autism spectrum disorder (ASD) symptoms." (PMID 33468258, 2021). "Mutations in the SHANK3 gene are a cause of autism spectrum disorder, which is characterized by impairments in social interaction and communication, and restricted behavioral patterns and interests." (PMID 34777208, 2021). "The strong genetic association of SHANK3 with autism spectrum disorder (ASD) emphasizes the importance of SHANK3 in neuronal development." (PMID 33568460, 2021). "Phelan-McDermid syndrome (PMS) is a rare neurodevelopmental disorder caused by haploinsufficiency of the SHANK3 gene and characterized by global developmental delays, deficits in speech and motor function, and autism spectrum disorder (ASD)." (PMID 34593045, 2021). "Multiple forms of SHANK3 mutation are also found in individuals with Phelan-McDermid Syndrome Contribution of SHANK3 mutations to autism spectrum disorder, schizophrenia, and bipolar disorder." (PMID 34504419, 2021). "Deletion or mutations of SHANK3 lead to Phelan–McDermid syndrome and monogenic forms of autism spectrum disorder (ASD)." (PMID 33203459, 2020). "SHANK3 mutations, including de novo deletions, have been associated with autism spectrum disorders (ASD)." (PMID 30918484, 2019). "Mutations in the SHANK3 gene have been associated with various brain disorders, including autism spectrum disorders (ASD), Phelan-McDermid Syndrome (PMS), schizophrenia, intellectual disability, and mania." (PMID 31649512, 2019). "Clinically, SHANK3 has been implicated in multiple neurodevelopmental and psychiatric disorders, including autism spectrum disorders (ASD), Phelan-McDermid syndrome (PMS), schizophrenia, intellectual disability, and mania." (PMID 31275112, 2019). "Phelan-McDermid syndrome (PMS) is caused by haploinsufficiency of the SHANK3 gene on chromosome 22q13.33 and is characterized by intellectual disability, hypotonia, severe speech impairments, and autism spectrum disorder." (PMID 31879555, 2019).
autism spectrum disorder (continued). "Mutations within the Shank3 gene are known to cause autism spectrum disorders (ASDs), which are characterized by impaired social interaction, communication skills and repetitive or restricted interests and behaviors." (PMID 30971895, 2019). "SHANK3 loss of function is one of the most frequently recurring alterations in autism spectrum disorder (ASD) and ID cohorts, with an estimated frequency at 0.5% to 2%, respectively." (PMID 31319798, 2019). "Shank3, an abundant excitatory postsynaptic scaffolding protein, has been associated with multiple brain disorders, including autism spectrum disorders (ASD) and Phelan-McDermid syndrome (PMS)." (PMID 31649512, 2019). "We previously identified de novo SHANK3 mutations in patients with autism spectrum disorders (ASD) and showed that SHANK3 represents one of the major genes for ASD." (PMID 30643170, 2019). "SHANK3 (ProSAP2) is among the most common genes mutated in autism spectrum disorders (ASD) and is the causative gene in Phelan–McDermid syndrome (PMS)." (PMID 31451607, 2019). "Shank3 is an excitatory postsynaptic scaffolding protein implicated in multiple brain disorders, including autism spectrum disorders (ASD) and Phelan-McDermid syndrome (PMS)." (PMID 30356810, 2018). "Deletions and mutations in the SHANK3 gene are strongly associated with autism spectrum disorder and underlie the autism-associated disorder Phelan–McDermid syndrome." (PMID 30064494, 2018). "Human genetic and genomic studies have supported a strong causal role of SHANK3 deficiency in autism spectrum disorder (ASD)." (PMID 29619162, 2018). "Haploinsufficiency for the SHANK3/ProSAP2 gene is believed to be one of the most common monogenic causes of autism spectrum disorder (ASD), accounting for approximately 0.5% of cases." (PMID 30064494, 2018). "Mutations within the SHANK family of genes (comprising SHANK1, PROSAP1/SHANK2 and PROSAP2/SHANK3) are over-represented in the autism spectrum disorder (ASD) population and are the cause of specific disorders such as Phelan-McDermid Syndrome." (PMID 29970986, 2018). "Haploinsufficiency of the SHANK3 gene, encoding for a scaffolding protein located in the postsynaptic density of glutamatergic synapse, has been linked to forms of autism spectrum disorders (ASDs)." (PMID 30364266, 2018). "Disruption of the human SHANK3 gene can cause several neuropsychiatric disease entities including Phelan-McDermid syndrome, autism spectrum disorder (ASD), and intellectual disability." (PMID 28261056, 2017). "Deletions, duplications, and point mutations of SHANK3 are associated with autism spectrum disorders, intellectual disability, schizophrenia, bipolar disorder, and attention deficit hyperactivity disorder." (PMID 28469556, 2017). "Phelan-McDermid syndrome (PMS), a neurodevelopmental disorder caused by deletion or mutation in the SHANK3 gene, is one of the more common single-locus causes of autism spectrum disorder (ASD)." (PMID 26909118, 2016). "miR-34a also regulates SHANK3, which encodes synaptic scaffolding proteins associated with autism spectrum disorders." (PMID 27920667, 2016). "SHANK3 is not only strongly implicated in autism spectrum disorders (ASD) but also plays a critical role in human Phelan-McDermid syndrome (22q13.3 deletion syndrome)." (PMID 27562614, 2016). "Mutations in SHANK genes, in particular SHANK2 and SHANK3, lead to autism spectrum disorders (ASD) in both human and mouse models." (PMID 27795858, 2016). "These genes include one that has been previously linked to SCZ, Autism Spectrum Disorder and Intellectual Disability (SHANK3) as well as two novel genes that were identified through a protein:protein interaction study (EP300 and MAPK14)." (PMID 26039597, 2015). "Shank3 is a postsynaptic scaffolding protein implicated in synapse development and autism spectrum disorders." (PMID 25852484, 2015).
autism spectrum disorder (continued). "SHANK3 has been described as one of the most promising candidate susceptibility genes for autism and autism spectrum disorders." (PMID 25997006, 2015). "SHANK3 has also been identified in gene-linkage studies to be associated with autism spectrum disorder (ASD)." (PMID 26306707, 2015). "Deletions and point mutations of SHANK3 are associated with Phelan-McDermid syndrome, autism spectrum disorders (ASDs), intellectual disability, schizophrenia and bipolar disorder." (PMID 26572867, 2015). "The genes Auts2 and Shank3 are associated with autism spectrum disorders and other neurological diseases, and in this study both of the genes exhibited an alteration in methylation pattern in the gene body." (PMID 24484737, 2014). "This study supports findings from previous research on the severity of intellectual, motor, and speech impairments seen in SHANK3 deficiency, and highlights the prominence of autism spectrum disorder in the syndrome." (PMID 23758760, 2013). "Loss of a functional copy of the SHANK3 gene leads to the neurobehavioral manifestations of 22q13 deletion syndrome and/or to autism spectrum disorders." (PMID 21167025, 2010). "In sharp contrast, two autism spectrum disorder-related SHANK3 variants (R12C and L68P) within the SPN domain that are unable to bind to Rap1–GTP failed to block activation of Rap1 or αVβ3 in response to optogenetic recruitment of talin to the plasma membrane of endothelial cells." (PMID 39853211, 2025). "Furthermore, dogs with Shank3 mutations, which represent a promising complementary animal model of autism spectrum disorders (ASD), show a loss of interbrain coupling and reduced attention during human–dog interactions." (PMID 39257367, 2024). "To clarify the pathogenicity of this variant in SHANK3 we began to compare the functional effects of this mutation with those of other variants in SHANK3 which are associated with autism spectrum disorders (ASD), intellectual disability (ID) or other disorders such as epilepsy." (PMID 35042901, 2022). "Furthermore, variants in SHANK3 are also associated with intellectual disability in 2%, autism spectrum disorder in 0.5–2%, and schizophrenia in 0.6–2.16% of cases." (PMID 35328058, 2022). "SHANK3 is a scaffolding protein implicated in autism spectrum disorders (ASD)." (PMID 35734418, 2022). "Deletion/mutation of the Shank3 in humans and mice is related to autism spectrum disorder." (PMID 36672612, 2022). "For PMS patients with autism spectrum disorders carrying SHANK3 mutations, a rational approach could also be the use of histone deacetylase (HDAC) inhibitors." (PMID 35328058, 2022). "SHANK3 is also associated with intellectual disability, autism spectrum disorder and schizophrenia." (PMID 35328058, 2022). "SH3 and Multiple Ankyrin Repeat Domains 3 (SHANK3)-caused autism spectrum disorder (ASD) may present a unique opportunity to clarify the heterogeneous neuropathological mechanisms of ASD." (PMID 34776852, 2021). "In the experiments on mice carrying Shank3 mutation (a model of autism spectrum disorder (ASD)), we have recently found dramatic changes in S-nitrosylation of proteins responsible for the synaptic vesicle cycle, neurotransmission and neurodevelopment in the cortices of these mice." (PMID 32429146, 2020). "Moreover, SHANK2 and SHANK3 have been shown to be causative genes for autism spectrum disorders, possibly through the regulation of RAC1 function." (PMID 32616021, 2020). "Moreover, genetic studies have identified point mutations in the SHANK3 gene in cases of autism spectrum disorder (ASD) that establish the causal role of SHANK3 mutations in ~ 1% of individuals with ASD." (PMID 29619162, 2018).
autism spectrum disorder (continued). "Genetic defects in the three SH3 and multiple ankyrin repeat domains (SHANK) genes (SHANK1, SHANK2, and SHANK3) are associated with multiple major neuropsychiatric disorders, including autism spectrum disorder (ASD), schizophrenia (SCZ), and bipolar disorder (BPD)." (PMID 30505269, 2018). "Similarly, we observed novel sex differences in the SHANK2 and SHANK3 scaffolding protein genes that have been associated with autism spectrum disorders." (PMID 26553366, 2015). "We identified a mutation in SHANK3 that underscores its relevance in Autism Spectrum Disorder." (PMID 25646853, 2015). "Mutations of the SHANK3 gene have been associated with autism spectrum disorder." (PMID 25997006, 2015). "We hypothesize that SHANK3 haploinsufficiency may lead to alterations in the inhibitory system, which could be linked to the excitatory/inhibitory imbalance observed in models of autism spectrum disorder (ASD)." (PMID 37528484, 2023). "Shank3, a postsynaptic scaffolding protein involved in regulating excitatory synapse assembly and function, has been implicated in several brain disorders, including autism spectrum disorders (ASD), Phelan-McDermid syndrome, schizophrenia, intellectual disability, and mania." (PMID 31275112, 2019). "The SHANK3 gene encoding core scaffolding proteins at glutamatergic postsynapse is a typical dosage-sensitive gene, both deletions and duplications of which are associated with Phelan-McDermid syndrome, autism spectrum disorders, bipolar disorder, intellectual disability, or schizophrenia." (PMID 26572867, 2015). "Research on autism spectrum disorder (ASD) suggests that variations in SHANK3 mRNA levels can impact hippocampal synaptic transmission in mice, potentially leading to long-term deficits in learning and memory." (PMID 39596417, 2024). "Because of its key role in autism spectrum disorder, Shank3 mice have chiefly been investigated at a young age." (PMID 37253603, 2023). "We further validated Shank3, an important ASD (Autism spectrum disorder) risk gene that is critically involved in regulating synaptic plasticity, and found it was significantly decreased in the stressed males, but not in females." (PMID 36829105, 2023). "A more complex disruption of SHANK3 protein results in more concordant and replicable behavioral deficits related to autism spectrum disorders." (PMID 35884680, 2022). "Mutations or deletions of the SHANK3 gene are causative for Phelan–McDermid syndrome (PMDS), a syndromic form of autism spectrum disorders (ASDs)." (PMID 35726031, 2022). "The mRNA expression levels of NLGN3 and SHANK3 were found to be significantly decreased in individuals with autism spectrum disorder (ASD) compared to the controls." (PMID 33672431, 2021). "As an excitatory synapse scaffolding protein, SHANK3 plays a critical role in synapse structure and function and has a strong genetic linkage to autism spectrum disorder (ASD)." (PMID 33568460, 2021). "Mutations and deletions in the SHANK3 gene cause the major neurodevelopmental features of Phelan–McDermid syndrome (PMS), which is characterized by intellectual disability, autism spectrum disorder, and sensory hyporeactivity." (PMID 34313403, 2021). "Phelan-McDermid syndrome (PMS) is a rare genetic disorder with high risk of autism spectrum disorder (ASD), intellectual disability, and language delay, and is caused by 22q13.3 deletions or mutations in the SHANK3 gene." (PMID 32560742, 2020). "Partial or an entire deletion of SHANK3 are considered as major drivers in the Phelan–McDermid syndrome, in which 75% of patients are diagnosed with autism spectrum disorder (ASD)." (PMID 32807217, 2020). "Several studies show that SHANK3 is responsible for autism spectrum disorders (ASDs), intellectual disability (ID), and schizophrenia." (PMID 32982797, 2020).